EPO (erythropoietin)
Diseases named in the same sentence as EPO in open-access papers (continued):
Sharing a sentence is not in itself a finding about the gene and the disease.
glaucoma (continued). "This led to the suggestion that erythropoietin may have a potential therapeutic role as a neuroprotector in glaucoma." (PMID 25914734, 2015). "In this study, we compared the aqueous concentration of EPO in eyes with primary open angle glaucoma (POAG), pseudoexfoliative glaucoma (PXFG), and neovascular glaucoma (NVG) to the EPO concentration in the aqueous humor of age-matched control subjects with cataracts." (PMID 22876126, 2012). "The role of EPO in the pathophysiology of glaucoma needs to be investigated further." (PMID 22876126, 2012). "However, studies have shown that EPO also has neuroprotective effects and may be useful for rescuing apoptotic retinal ganglion cells in glaucoma." (PMID 36769310, 2023). "However, the discussion of EPO in the treatment of glaucoma is limited to animal studies." (PMID 35806148, 2022). "Erythropoietin (EPO) is neuroprotective in multiple models of neurodegenerative diseases, including glaucoma." (PMID 36978804, 2023). "In this review, we discuss the correlation between glaucoma and EPO, physiology and potential neuroprotective function of the EPO/EPOR system, and latest evidence for the treatment of glaucoma with EPO." (PMID 36555679, 2022). "In other clinical researches, EPO and PDGF were found to increase in the aqueous humor of patients with primary angle closure glaucoma, primary open angle glaucoma and neovascular glaucoma." (PMID 34384366, 2021). "In our review of animal studies concerning the local or systemic administration of EPO in glaucoma, no significant adverse events were reported." (PMID 36555679, 2022). "A previous study evaluated the effects of EPO on RGCs in episcleral vessel cautery-induced rats with glaucoma using 200ng EPO, which found no significant decrease in the RGC of the EPO-treated group." (PMID 32302311, 2020). "There was not a statistically significant difference between eyes with and without controlled IOP in terms of aqueous humor EPO concentration in each type of glaucoma separately (all p-values >0.05)." (PMID 22876126, 2012). "To date, human studies using EPO for the treatment of glaucoma are still lacking." (PMID 35806148, 2022). "Although the potential benefits of exogenous EPO in glaucoma have been verified in many animal studies, there are no randomized controlled trials in the literature investigating the possible therapeutic effect of EPO in humans with glaucoma." (PMID 36555679, 2022). "However, to our knowledge, there are no ongoing clinical trials of EPO therapy for glaucoma." (PMID 30524222, 2018). "Erythropoietin (EPO) and its non-hematopoietic derivative EPO-R76E have been identified as potent neuroprotective agents in glaucoma models." (PMID 40943905, 2025).
myeloma (21 papers, 1982 to 2024). "Consequently, our observation that EPO-mediated ERK activation in myeloma cells is associated with reduced viability and adds to a growing list of instances of ERK activation concomitant with cell death." (PMID 27581518, 2016). "In three patients with multiple myeloma who received thalidomide, type C interaction with EPO was observed in our study." (PMID 38029231, 2023). "Only three cases (1.3%) of type C interaction of EPO with thalidomide were reported in patients with multiple myeloma." (PMID 38029231, 2023). "In certain cancers, such as multiple myeloma, recombinant EPO was shown to downregulate angiogenic factors." (PMID 32785675, 2020). "In another relevant study, it was found that mice (5T33MM murine myeloma model) treated with EPO showed accelerating bone resorption as measured by μ-CT, and was suggested to be caused by activation of bone marrow-derived macrophages." (PMID 27581518, 2016). "EPO-mediated EPOR signaling reduced the viability of myeloma cell lines and of malignant primary plasma cells in vitro." (PMID 27581518, 2016). "Examination of primary myeloma cells for their putative active EPO/EPOR signaling revealed that all samples (MM-51-MM-54) exhibited activation of both ERK-1/2 and JAK-2 after 5 min treatment with 10 U/ml rhEPO." (PMID 27581518, 2016). "Decreased viability and proliferation were observed with increasing concentrations of rhEPO, suggesting an inhibitory role of EPO on myeloma cells." (PMID 27581518, 2016). "The concomitant observation that higher EPOR expression is associated with survival in four different therapy strategies should encourage further studies to reveal the relevance of EPO/EPOR signaling in multiple myeloma progression." (PMID 27581518, 2016). "Exposure to recombinant human EPO (rhEPO) reduced viability of INA-6 myeloma cell line and of primary myeloma cells." (PMID 27581518, 2016). "Here, we demonstrate that the EPOR is expressed on the cell surface of myeloma cell lines and on primary myeloma cells, and show for the first time active EPO/EPOR signaling in malignant plasma cells." (PMID 27581518, 2016). "Increases in phosphorylation of ERK-1/2 and JAK-2 were observed, suggesting that the EPO/EPOR signaling complex is functional in myeloma cells." (PMID 27581518, 2016). "Our results encourage further studies to investigate the importance of EPO/EPOR in multiple myeloma progression and treatment." (PMID 27581518, 2016). "Together, our results suggest that EPO reduces the viability of primary myeloma cells in an EPOR-dependent manner and that the cells cannot be rescued by stroma cells." (PMID 27581518, 2016). "As increased IL-12 secretion appears to be the dominant feature, DCs show increased effects against myeloma cells after the addition of EPO both in vitro and in vivo." (PMID 22094132, 2012). "In the same in vivo model, EPO-treated myeloma mice show a prolonged survival and a preserved production of polyclonal immunoglobulins by B cells." (PMID 22094132, 2012). "JAK2 could be phosphorylated by recombinant EPO in kinase assay and EPO exposure intriguingly reduced myeloma cell survivals." (PMID 34680295, 2021). "Previous investigators also explored how EPO affected the immune status of patients with multiple myeloma and found that the immunomodulatory effects of EPO on lymphocytes, which lack the EPOR, were indirect and occurred by activating macrophages that express EPOR6." (PMID 29391474, 2018). "It has been a concern that EPO, through its pro-proliferative effect in pre-erythrocytes, might enhance myeloma cell growth." (PMID 27581518, 2016). "In order to investigate whether there was an autocrine EPO/EPOR signaling in myeloma cells, we measured expression of EPO mRNA in 20 of the samples." (PMID 27581518, 2016). "The role of EPO/EPOR is still unclear in the pathogenesis of multiple myeloma." (PMID 27581518, 2016).
myeloma (continued). "Together, this study shows that primary myeloma cells display active EPO/EPOR signaling and that rhEPO may induce myeloma cell death in vitro, both in monoculture and in co-culture of primary cells with myeloma-derived bone marrow stroma cells." (PMID 27581518, 2016). "In another relevant study, EPO was used together with granulocyte colony stimulation factor (G-CSF) to see if eltrombopag (small non-peptide molecule that stimulates megakaryopoises in bone marrow) affected the proliferative capacity of human myeloma cells." (PMID 27581518, 2016). "Based on the survival studies, it is therefore intriguing to speculate whether active EPO/EPOR signaling may be favourable for the survival of myeloma patients." (PMID 27581518, 2016). "Nevertheless, given that growth factors may be prescribed for some patients with multiple myeloma, we wanted to determine whether eltrombopag may synergistically interact with EPO and G-CSF to promote proliferation of human myeloma cells." (PMID 25886818, 2015). "By contrast, EPO may promote the clonal expansion and cytokine production by T cells, because the administration of EPO to mice suffering from multiple myeloma stimulates an anti-tumor immune response via CD8+ T cells activation." (PMID 22094132, 2012). "Interestingly, a recent study has demonstrated that EPO/EPOR could reduce the variability of myeloma cell lines and malignant primary plasma cells." (PMID 38149248, 2023). "Together, these results suggest that EPO/EPOR signaling may operate in myeloma cells." (PMID 27581518, 2016). "We show here that EPO/EPOR signaling is functional in both primary myeloma cells and cell lines and that recombinant human EPO exhibits a negative effect on myeloma cell viability in vitro." (PMID 27581518, 2016). "Co-cultures of primary myeloma cells with bone marrow-derived stroma cells did not protect the myeloma cells from EPO-induced death, while the stroma cells were unaffected." (PMID 27581518, 2016). "Apoptosis of CD138+ myeloma cells was not altered by either eltrombopag at concentrations up to 10 μM or 100 ng/ml rhTPO in the presence or absence of G-CSF and EPO." (PMID 25886818, 2015). "Treatment of myeloma cells with EPO was followed by JAK-2 and ERK-1/2 phosphorylation while knockdown of EPOR expression in the myeloma cell line INA-6 reduced JAK-2 and ERK-1/2 phosphorylation, again demonstrating the specificity of active EPO/EPOR signaling in myeloma cells." (PMID 27581518, 2016). "All samples tested were found negative for EPO mRNA (data not shown), suggesting that plasma cells do not normally express significant amounts of EPO and that EPO signaling in myeloma may occur through a paracrine or endocrine mechanism." (PMID 27581518, 2016). "Furthermore, no synergistic effect on myeloma cell growth was noted with the combination of eltrombopag, EPO, and G-CSF, and eltrombopag did not appear to reverse the cytotoxic or apoptotic effects of lenalidomide or bortezomib." (PMID 25886818, 2015). "Hypoxia-dependent erythropoietin (EPO)-receptor (EPOR) signaling is central in various cancers, but the relevance of EPOR signaling in multiple myeloma cells has not yet been thoroughly investigated." (PMID 27581518, 2016). "Our results demonstrate that eltrombopag, in combination with EPO and G-CSF, did not enhance the proliferation of primary human CD138+ myeloma cells or myeloma cell lines." (PMID 25886818, 2015).
Sleep apnea (21 papers, 2009 to 2025). An intermittent cessation of airflow at the mouth and nose during sleep is known as sleep apnea. "Elevated EPO is also caused by hypoxemia in some cases of chronic pulmonary disease, shunt infection and sleep apnea." (PMID 19946506, 2009). "Both subjects exhibited mild to moderate sleep apnea, while their erythropoietin levels were within the normal range." (PMID 41431006, 2025). "Six-month administration of acetazolamide, a carbonic anhydrase inhibitor, stimulated respiratory response and rectify hypoxemia, and thus reduced Hct, EPO and pulmonary vascular resistance and even improved sleep-related breathing disorders." (PMID 39257892, 2024). "Currently available data regarding the blood levels of erythropoietin (EPO) in sleep apnea (SA) patients are contradictory." (PMID 28280920, 2017). "The only minor criterion is a subnormal erythropoietin level, which helps differentiate PV from secondary erythrocytosis caused by non-neoplastic factors such as smoking, sleep apnea, and testosterone use." (PMID 40507313, 2025). "Together, these studies suggested that EPO could be used as a target drug to protect against the harmful consequences of sleep-disordered breathing." (PMID 34594222, 2021). "In addition, we also tested the effect of EPO treatment on other behavioral paradigms for anxiety and depression, since such problems are frequently encountered in patients with sleep apnea, as well as with IH-exposures." (PMID 22759774, 2012). "Fifth, except two included studies (subjects in one study was CSA, the other one was sleep-disorder breathing), subjects in the most remain studies were OSA, it was difficult for us to evaluate the influence of SA type on serum EPO levels." (PMID 28280920, 2017). "Patient also presented with secondary erythrocytosis (Haemoglobin 195, janus kinase 2 [Jak2] negative, with increasing erythropoietin [EPO] level), attributed to severe sleep apnea and asthma." (PMID 37206271, 2023). "EPO, in general, drops with hypoxemia treatment in COPD and sleep apnea." (PMID 34068590, 2021).
cerebral infarction (19 papers, 2009 to 2025). An ischemic condition of the brain, producing a persistent focal neurological deficit in the area of distribution of the cerebral arteries. "Inclusion of older patients with multiple risk factors for hemodialysis, usage of erythropoietin, and advanced diagnostic facilities in the form of magnetic resonance imaging (MRI) were some of the reasons reported for the increased incidence and recognition of brain infarcts in CKD patients." (PMID 20352003, 2009). "EPO has been used to reduce vasospasm in sub-arachnoid haemorrhage in a randomized controlled trial, which was associated with reduced DIND with new cerebral infarcts, a reduction of impaired auto-regulation and better outcome at discharge." (PMID 26463364, 2015). "For example, an animal model with increased expression of endogenous EPO exhibits increased cerebral infarct size following arterial occlusion in spite of high levels of EPO within the brain." (PMID 21766022, 2011). "The results indicated that JCT could treat ICS by reducing the symptoms of cerebral infarction and enhancing neuroprotective effects, and its action mechanisms were associated with the activation of the HIF-1α/EPO/VEGFA pathway." (PMID 36269045, 2022). "In addition, treatment with EPO‐producing fibroblasts was associated with a higher density of proliferating cells, NSPCs, or neuroblasts in the SVZ after cerebral infarct." (PMID 30920178, 2019). "This may be due to the increased risk of cerebral hemorrhage in MHD patients with elevated blood pressure due to high doses of EPO, as well as the increased incidence of cerebral infarction due to the increased hemoglobin level and increased blood viscosity caused by EPO." (PMID 41244199, 2025). "At 4 h after the beginning of the experiment, HIF-1α and EPO in the HBO group increased, and the volume of cerebral infarction decreased." (PMID 39139771, 2024).
hyperparathyroidism (19 papers, 2011 to 2024). Hyperfunction of the parathyroid glands resulting in the overproduction of parathyroid hormone. "The cause of EPO hyporesponsiveness is unclear but may be related to hyperparathyroidism, inflammation, and nutritional status in CKD patients." (PMID 35937691, 2022). "The pathogenesis of renal anemia is multifactorial; presence of erythropoietin inhibitors, inadequate dialysis and low Kt/V, hyperparathyroidism and chronic inflammation." (PMID 32723294, 2020). "Hyperparathyroidism might affect EPO synthesis, erythrocyte survival, and bone marrow fibrosis contributing to ESA resistance." (PMID 33293895, 2020). "Therefore, we speculated that gut microbiota may affect EPO reactivity through hyperparathyroidism, hematopoietic raw materials, and inflammation." (PMID 35937691, 2022). "Additionally, it has been established that vitamin D directly increases erythropoietin sensitivity in people suffering from kidney dysfunction, and lack of vitamin D is associated with hyperparathyroidism, which leads to a decrease in endogenous erythropoietin production." (PMID 39435383, 2024). "Moreover, there are many confounders (our patients were likely to be prescribed aluminium because of poor phosphate control and thus EPO resistance may be secondary to hyperparathyroidism rather than Aluminium toxicity)." (PMID 21992770, 2011).
Thromboembolism (19 papers, 2011 to 2026). The formation of a blood clot inside a blood vessel that subsequently travels through the blood stream from the site where it formed to another location in the body, generally leading to vascular occlusion at the distant site. "We carefully explore patients on underlying malignant diseases or risk of thromboembolism to limit this potential side effect of EPO." (PMID 22672319, 2012). "The two potential limiting side-effect of chronic use of EPO for neuroprotection are increased risk of thromboembolism and its proproliferative effects on preexisting neoplasia." (PMID 22046448, 2011). "Rapid elevation of the erythropoietin concentration may result in a sudden increase in Hb, which may increase the risk of thromboembolism." (PMID 38792306, 2024). "Accordingly, compared with CERA, HIF-PH inhibitors are hypothesized to maintain a physiological concentration of erythropoietin and thereby reduce the risk of thromboembolism." (PMID 38792306, 2024). "Since erythropoietin’s use was associated to a possible risk of thromboembolism, we performed regular clinical and laboratory monitoring of LT candidates on erythropoietin treatment also in consideration that the waiting time for a suitable deceased donor is unpredictable." (PMID 32000668, 2020). "However, EPO triggers profound haematopoiesis that increases the risk of thromboembolism." (PMID 22462027, 2012). "Erythropoietin (EPO) has tissue-protective properties, but it increases the risk of thromboembolism by raising the haemoglobin concentration." (PMID 22462027, 2012). "EPO could have either a tissue-protecting effect through anti-apoptosis, neuroprotection, cyto-protection, or potentially unfavorable effects through thromboembolism, extreme erythropoietic effect, and impaired microcirculation." (PMID 38539151, 2024). "Similarly, erythropoietin (EPO) has tissue-protective properties, but increases the risk of thromboembolism by raising haemoglobin concentration." (PMID 23320245, 2012). "An alternate strategy would be to consider non-erythropoietic forms of EPO, which retain their neuroprotective properties but lack proproliferative effects on myeloid tissues and are projected not to induce thromboembolism." (PMID 22046448, 2011).